ADA (adenosine deaminase)
Diseases named in the same sentence as ADA in open-access papers (continued):
Sharing a sentence is not in itself a finding about the gene and the disease.
diabetes (continued). "Furthermore, alteration in ADA activity was demonstrated in many cardiovascular pathologies such as atherosclerosis, myocardial ischemia-reperfusion injury, hypertension, thrombosis, or diabetes." (PMID 33053898, 2020). "Smoking and alcohol consumption decreased serum ADA concentrations in patients with ACI, whereas diabetes and hypertension had the opposite effect." (PMID 36260871, 2022). "In our present study, serum ADA levels were observed to be positively correlated with ageing, higher SBP, longer diabetes duration, and increased levels of ALT, AST, GGT, CysC and HbA1c and negatively correlated with eGFR and insulin sensitivity index (IS-CP)." (PMID 36267565, 2022). "Age, SBP, diabetes duration, current smoking, ALT, GGT, CysC and HbA1c increased with ascending serum ADA quartile, whereas eGFR and insulin sensitivity index (IS-CP) decreased." (PMID 36267565, 2022). "In diabetes, ENT-mediated transport is the main mechanism that cleared extracellular adenosine, while under control conditions ADA played a greater functional role." (PMID 26879172, 2016). "Although multiple studies have shown that serum ADA levels are significantly increased in patients with diabetes, no study has reported the relationship between serum ADA levels and DKD in patients with T2D." (PMID 34319903, 2021). "Total serum ADA activity, specially that due to ADA2, could be useful test for the diagnosis of type 2 (or II) diabetes mellitus." (PMID 28050278, 2016). "ADA increase, especially ADA2, may serve as an immunoenzyme marker in the pathology of type 2 diabetes mellitus." (PMID 28050278, 2016). "However, only a few studies have investigated the function of ADA in autoimmune diseases and type 2 diabetes mellitus, and no significant work has elucidated its effect on lipid accumulation." (PMID 35893142, 2022). "Unlike what happened when treating diabetic rats with ADA, ADORA3 antagonism does not significantly affect the levels of IL-10, while only attenuates the levels of IL-6 found in diabetes." (PMID 31540220, 2019). "In whole retina extracts, after 7 days of diabetes induction by STZ injection, the retinal AK and ADA protein levels were not significantly different from the levels observed in control animals." (PMID 23840723, 2013).
leukemia (23 papers, 1975 to 2024). A malignant (clonal) hematologic disorder, involving hematopoietic stem cells and characterized by the presence of primitive or atypical myeloid or lymphoid cells in the bone marrow and the blood. "Leukemia and myelodysplasia arose in a gammaretroviral gene therapy trial for adenosine deaminase-deficient severe combined immune deficiency (ADA-SCID), representing a setback; however, this side effect led to the development of the self-inactivating (SIN) γ vector." (PMID 37780116, 2023). "Highest levels of Ada are found in cells of the lymphoid system, explaining why ADA deficiency causes SCID, and why ADA is a common target for leukemia chemotherapies." (PMID 35383287, 2022). "Other bacteria and archaea were found to contain the repetitive sequence that Ishino first discovered in E. coli.Gene therapy induced leukaemia in ADA-SCID patients." (PMID 36678404, 2022). "Adenosine deaminase (ADA), which catalyzes the irreversible deamination of adenosine to inosine, is related to various human diseases such as tuberculous peritonitis and leukemia." (PMID 31216643, 2019). "The lower frequency of leukemia in the ADA-SCID cohort might be influenced by several factors among which we can list the function of the transgene, the disease background and other yet unknown factors." (PMID 38688902, 2024). "In contrast, the high level of ADA activity may result in several serious diseases such as tuberculous peritonitis and leukemia." (PMID 31216643, 2019). "Over activity of ADA is associated with AIDS, leukemia, stresses and Parkinson." (PMID 23351306, 2012). "Besides, the type of bioactivity in two different isolates of the same species differed with respect to sensitivity to adenosine deaminase and relative activity towards leukemia cells and thrombocytes (ND53 and 73)." (PMID 20098602, 2009). "Pentostatin, a nonspecific ADA inhibitor has been clinically used for the treatment of leukemia and lymphoma." (PMID 37371990, 2023). "For example, none of the 10 patients in a clinical study developed leukemia, and among a total of 50 ADA-SCID patients treated with γRV, only one showed clinical evidence of leukemia." (PMID 36992407, 2023). "Our research results showed that the expression of ADA protein in T-ALL tumor cells was higher than that in tumor cells from AML patients, suggesting a specific difference in ADA-mediated signal transduction and cytokine secretion between the two types of leukemia." (PMID 37266435, 2023). "However, in contrast to the SCID-X1 trials, out of more than 30 patients with adenosine deaminase deficiency SCID (ADA-SCID) treated with gammaretroviral gene therapy over more than 10 years, none have developed leukaemia." (PMID 25365582, 2014). "MLV-based retroviral vectors were used in both SCID-X1 and ADA-SCID trials, yet in contrast to the SCID-X1 trials no recipients in the ADA-SCID trials developed clonal dominance or leukaemia." (PMID 25365582, 2014).
empyema (22 papers, 2011 to 2026). An accumulation of pus in a body cavity, usually the pleural space. "Our previous study demonstrated that in adults, empyema was reported in 8.9% of patients with pleural TB and significant associations between several clinical characteristics (such as sex, pleural adenosine deaminase (ADA), white blood cell (WBC), and pulmonary TB) and presence of TE were observed." (PMID 34778142, 2021). "High ADA levels can also be observed in patients with empyema, malignancy, para-pneumonic effusions, rheumatoid pleurisy, and some other infectious diseases such as brucellosis." (PMID 36264250, 2022). "Among the PPE subgroups, the severity of pleural cell damage was least in UPPE and greatest in empyema, leading to increased LDH levels and corresponding increases in the LDH/ADA ratio in the 3 subgroups." (PMID 29202740, 2017). "Adenosine deaminase (ADA), C Reactive Protein (CRP) and granulocyte count are all used in the differential diagnosis of tuberculous effusions, parapneumonic effusions and empyema." (PMID 28545517, 2017). "The diagnostic accuracy of CD4+IL-9+, CD4+IL-17+, CD4+IL-22+, CD4+CD25+FOXP3+ T cells, and ADA in the differentiation of tuberculous from non-tuberculous effusions (malignant, empyema, and parapneumonic effusions)." (PMID 34925358, 2021). "However, there were significant differences in pleural fluid LDH/ADA ratios between patients with TPE and each of the PPE subgroups (UPPE, CPPE, or empyema) [P < .0001 for each subgroup]." (PMID 29202740, 2017). "However, a similar or even higher ADA level has occasionally been reported in PPE, particularly in patients with empyema." (PMID 29202740, 2017). "Our findings revealed a significantly lower pleural fluid LDH/ADA ratio in the TPE group compared with the PPE group (P < .0001) and this difference was also evident in comparison with the 3 PPE subgroups (UPPE, CPPE, and empyema) [P < .0001]." (PMID 29202740, 2017). "Despite improved detection rates with new methods, high pleural fluid levels of adenosine deaminase (ADA) may be found in other diseases, especially empyema and parapneumonic effusions, and there is no established cut-off value for measurement of interferon-gamma in pleural fluid." (PMID 21819571, 2011).
autoimmune disease (21 papers, 2015 to 2025). A disorder resulting from loss of function or tissue destruction of an organ or multiple organs, arising from humoral or cellular immune responses of the individual to their own tissue constituents. "Furthermore, ADA is closely associated with inflammation, autoimmune diseases, acquired immune deficiency syndrome, and tumors, with its concentration positively correlating with disease severity." (PMID 35986367, 2022). "Through its binding with the adenosine deaminase (ADA), this molecule can contribute to autoimmune diseases and cancers, conditions where serum DPP-4 activity and sDPP-4 levels are found altered." (PMID 40072115, 2025). "Recently, elevated levels of ADA in sera have been described in autoimmune diseases, including SLE and juvenile rheumatoid arthritis (JIA)." (PMID 35090387, 2022). "Increased ADA activity has been observed in some immune-related diseases, such as inflammation, tumor, and autoimmune diseases." (PMID 35090387, 2022). "For example, the ADA level is notably elevated in Mycobacterium tuberculosis infection, autoimmune diseases, hepatitis, and malignant tumors." (PMID 35986367, 2022). "Accumulating research has explored ADA deregulation in many types of autoimmune diseases, but few data are available in MS." (PMID 33007809, 2020). "To date, accumulating data have suggested an important role of adenosinergic pathway-related molecules (i.e., CD39, CD73, ADA, adenosine receptors, etc.)in many types of human autoimmune diseases." (PMID 27665459, 2016). "Increased ADA has been observed in many autoimmune diseases, such as SLE and RA." (PMID 40852723, 2025). "In addition, increased serum ADA levels were shown to have potential value in the diagnosis and surveillance of these autoimmune diseases." (PMID 36267565, 2022). "Since the ADA is an enzyme involved in autoimmune diseases and cancer development, it is plausible to hypothesize that the DPP4 involvement in ADA-mediated pathways is at the basis of the elevated sDPP4 levels reported in these diseases." (PMID 36140405, 2022).
breast carcinoma (21 papers, 2013 to 2025). "However, elevated ADA activity in the pleural fluid has been associated with a number of malignant neoplasms, including non-Hodgkin’s lymphoma and breast cancer." (PMID 25667674, 2015). "Studies have shown that ADA inhibition decreases tumor size and tumor growth in mouse models of breast cancer and human breast cancer cells as well." (PMID 41360777, 2025). "Elevated ADA activity promotes the progression of breast cancer, colorectal cancer, gastric cancer, renal cell carcinoma, and other tumours." (PMID 38556542, 2024). "Several previous studies have shown that altered ADA activity is related to the progression of a variety of tumors, especially in breast cancer." (PMID 35844514, 2022). "The inhibition of ADA by 2′deoxycoformycin (dCF) has been reported to reduce tumor size and its growth in mice with modeled breast cancer in vivo and in human tumor cells in vitro." (PMID 35327609, 2022). "It has been revealed that ADA was served as a potential therapeutic target for breast cancer and a biomarker in oral cancer." (PMID 34195087, 2021). "As breast cancer cells are a minor source of soluble ADA, we exclude the possibility of anchoring cancer cell-derived ADA on endothelial cells." (PMID 33916440, 2021). "Next, we analyzed the relation between macrophage polarization profile and plasma ADA iso-enzyme activities in breast cancer patients." (PMID 33916440, 2021). "IL-6, ADA and PAI secreted by MCF7 cells in the PDS-model were significantly associated to high grade breast cancer subtypes." (PMID 34090457, 2021). "We conclude that alterations in both ADA iso-enzymes can play a role in breast cancer development and progression by the modulation of extracellular adenosine-dependent pathways." (PMID 33916440, 2021). "The main ADA isoform found in all analysed cells, including endothelial cells, immune cells and breast cancer cells was ADA1." (PMID 30291675, 2018). "As there are only a few reports on ADA activity in breast cancer patients and unclear data about its origin, we also investigated the sources of ADA activity in murine and human cells engaged in tumour development." (PMID 30291675, 2018). "The aim of this study was to test the effects of adenosine deaminase inhibition by 2′deoxycoformycin (dCF) on the breast cancer development." (PMID 30291675, 2018). "This study highlights beneficial effects of adenosine deaminase inhibition on breast cancer development." (PMID 30291675, 2018). "The efficiency of adenosine deaminase inhibition by dCF was also evaluated in murine 4T1 breast cancer cells and murine H5V heart endothelial cells." (PMID 30291675, 2018). "The present study highlights low‐dose adenosine deaminase inhibition as a potential therapeutic strategy for breast cancer." (PMID 30291675, 2018). "Nevertheless, an elevated ADA activity in pleural fluid has also been reported in some cases of benign or malignant diseases, such non-Hodgkin’s lymphoma, breast cancer." (PMID 23514274, 2013). "Moreover, a correlation between ADA expression, breast cancer stage, and metastatic potential has been reported, making restoration of the normal ADA expression pattern an interesting therapeutic target." (PMID 39267843, 2024). "encoded adenosine deaminase (ADA)into an oncolytic targeted herpes virus to improve enzyme secretion for the metabolism of adenosine, and the clearance of adenosine within the TME reversed HER2-positive breast cancer resistance to trastuzumab." (PMID 36189223, 2022). "Although the exact effect of currently used breast cancer therapies on ADA activities require further studies, we believe that novel strategies, which based on modulating ADA activities may be important in enhancing their effectiveness." (PMID 33916440, 2021). "Then, plasma activities of total ADA and its isoenzymes were determined in breast cancer patients." (PMID 33916440, 2021).
breast carcinoma (continued). "Furthermore, it activated apoptosis by targeting the ornithine decarboxylase and adenosine deaminase pathway in breast cancer cell lines MCF-7 and MDA-MB-231." (PMID 32872275, 2020). "To investigate the cellular origin of ADA in carcinogenesis, we measured its activity in different types of murine and human cells engaged in tumour development, such as endothelial cells, immune cells (monocytes/macrophages) and breast cancer cells." (PMID 30291675, 2018). "It has been also speculated that elevated ADA activity in serum and breast cancer tissues may originate from other sources than tumour cells." (PMID 30291675, 2018). "Furthermore, this study introduces possible mechanisms of the control of breast cancer growth by adenosine deaminase inhibitor via adenosine receptor‐dependent and independent processes." (PMID 30291675, 2018). "We suggest that both ADA iso-enzymes could be valuable therapeutic targets in the breast cancer." (PMID 33916440, 2021). "Several lines of evidence suggest that altered adenosine deaminase (ADA) activity, especially its ADA2 iso-enzyme, is associated with malignant breast cancer (BC) development." (PMID 33916440, 2021). "However, there are few studies on the prognostic value of β2-mg, D-dimmer, 5’ NT, ADA and LAP in breast cancer at present." (PMID 37007080, 2023). "Some evidence suggests that changes in adenosine deaminase (ADA) activity, particularly its ADA2 isoenzyme, are related to the development of malignant breast cancer (BC)." (PMID 35242705, 2022). "Up to date, a potent anticancer effect of nonspecific adenosine deaminase inhibitor, erythro‐9‐(2‐hydroxy‐3‐nonyl)adenine (EHNA), was indicated against malignant pleural mesothelioma, but the effect of a specific ADA inhibition on the breast cancer development has never been studied." (PMID 30291675, 2018).
Wiskott-Aldrich syndrome (21 papers, 2014 to 2025). Wiskott-Aldrich syndrome (WAS) is a primary immunodeficiency disease characterized by microthrombocytopenia, eczema, infections and an increased risk for autoimmune manifestations and malignancies. "Somatic chimerism has been observed in several primary immunodeficiencies such as Wiskott Aldrich Syndrome, ADA-deficiency or X-linked SCID and is possibly associated with an amelioration of the clinical phenotype of disease." (PMID 25205547, 2014). "For instance, it has a positive clinical impact on ADA deficiency, Wiskott-Aldrich syndrome (WAS), Fanconi anemia, and in variants affecting DOCK8, ITGB2, or CXCR4." (PMID 40711587, 2025). "Retroviral gene therapy in autologous HSCs has provided clinical benefit in several PIDs including SCID-X1, Adenosine deaminase deficiency (ADA-SCID), Wiskott Aldrich Syndrome (WAS), and X-linked chronic granulomatous disease (X-CGD)." (PMID 35373187, 2022). "In humans, HSC kinetic data derived from the clonal tracking of their activityin vivo have been obtained from gene therapy clinical trials for adenosine deaminase (ADA) deficient-SCID and Wiskott-Aldrich syndrome (WAS)." (PMID 27081472, 2015). "Regarding the treatment perspectives, it is noteworthy that many IEI monogenic diseases appear to be good candidates for gene therapy, e.g., X-linked SCID and X-linked GCD, ADA-SCID and Wiskott-Aldrich Syndrome, and several clinical trials have already been accomplished." (PMID 35601409, 2022).